EGFR (epidermal growth factor receptor)
Diseases named in the same sentence as EGFR in open-access papers (continued):
Sharing a sentence is not in itself a finding about the gene and the disease.
Ventricular arrhythmia (2 papers, 2024). "Utilizing a Cox proportional risk model, they discerned a significantly elevated risk of ventricular arrhythmia in patients treated with EGFR-TKIs compared to those treated with platinum analogues." (PMID 39211774, 2024). "Despite the excellent antitumor effect, EGFR-TKIs could increase the risk of QT interval prolongation, which facilitates ventricular arrhythmia, possibly due to the interaction with potassium channel proteins of cardiomyocytes." (PMID 38774407, 2024). "In our study, no life-threatening ventricular arrhythmias were observed, and EGFR-TKI-induced QTc prolongation seemed benign." (PMID 38774407, 2024). "While cardiotoxic effects induced by EGFR-TKIs are often reversible and non-fatal after discontinuing or adjusting the medication, immediate attention is needed for life-threatening complications such as prolonged QT interval and ventricular arrhythmia." (PMID 39211774, 2024).
ventricular fibrillation (2 papers, 2022 to 2024). A disorder characterized by an electrocardiographic finding of a rapid grossly irregular ventricular rhythm with marked variability in QRS cycle length, morphology, and amplitude. "Interestingly, both pharmacological inhibition of EGFR and EGFR knockdown reduced the incidence of ventricular fibrillation induced by reperfusion." (PMID 36237897, 2022).
vitamin D deficiency (2 papers, 2020 to 2022). A nutritional condition produced by a deficiency of VITAMIN D in the diet, insufficient production of vitamin D in the skin, inadequate absorption of vitamin D from the diet, or abnormal conversion of vitamin D to its bioactive metabolites. "Therefore, we investigated the effects of a double treatment with losartan potassium (L), an AT1R antagonist, and the tyrosine kinase inhibitor erlotinib (E) on the alternative pathway of RFF related to TACE-dependent EGFR activation in 5/6-nephrectomized rats under vitamin D deficiency (D)." (PMID 33469545, 2020).
xeroderma pigmentosum group D (2 papers, 2013 to 2023). Any xeroderma pigmentosum in which the cause of the disease is a mutation in the ERCC2 gene. "A number of genetic variants have been reported to be associated with radiotherapy response for cancer, including XRCC1, X-ray repair cross complementing 2 (XRCC2), xeroderma pigmentosum group D (XPD), and EGFR." (PMID 36624463, 2023). "Three polymorphisms, which are excision repair cross-complementation 1 (ERCC1), xeroderma pigmentosum group D (XPD) and epidermal growth factor receptor (EGFR), were assessed in 257 postoperative stage II/III CRC patients with 5-fluorouracial chemotherapy in Taiwan." (PMID 23429196, 2013).
Achalasia (1 paper, 2021). A disorder of esophageal motility characterized by the inability of the lower esophageal sphincter to relax during swallowing and by inadequate or lacking peristalsis in the lower half of the body of the esophagus.
acoustic neuroma (1 paper, 2020). A type of benign brain tumor that begins in the Schwann cells, which produce the myelin that protects the acoustic nerve - the nerve of hearing. "At present, the efficacy of EGFR inhibitors in acoustic neuroma treatment is not ideal yet, which may be related to EGFR downregulated in some patients." (PMID 32733557, 2020).
acromegaly (1 paper, 2022). Acromegaly is an acquired disorder related to excessive production of growth hormone (GH) and characterized by progressive somatic disfigurement (mainly involving the face and extremities) and systemic manifestations. "Although EGFR and EGF are abundantly expressed in somatotroph adenomas, trials evaluating TKI in treatment of aggressive acromegaly are lacking." (PMID 36545335, 2022).
acute appendicitis (1 paper, 2021). "Patients undergoing surgery for acute appendicitis showed significantly elevated EGFR levels in the mesothelium when compared with patients undergoing elective surgery." (PMID 34916513, 2021). "We hypothesized that EGFR expression in mesothelial cells would be higher in acute appendicitis cases due to the bacterial contamination." (PMID 34916513, 2021). "Indeed, immunohistochemistry revealed a massive upregulation of EGFR in the whole mesothelium of patients with appendicitis when compared with patients undergoing elective non-contaminated surgery." (PMID 34916513, 2021). "In some acute appendicitis patients, the deposition of granulation tissue enriched in EGFR positive cells could be observed." (PMID 34916513, 2021).
acute liver failure (1 paper, 2025). Rapid deterioration of liver function causing encephalopathy and coagulopathy. "EGFR signaling is involved in the regulation of gene expression in endothelial cells, e.g. it has been shown that the tight junction protein occludin in brain endothelial cells of mice with acute liver failure was regulated by EGFR." (PMID 41574208, 2025).
acute monocytic leukemia (1 paper, 2016). Acute monoblastic leukemia (AML-M5), is one of the most common subtypes of acute myeloid leukemia (AML) that is either comprised of more than 80% of monoblasts (AML-M5a) or 30-80% monoblasts with (pro)monocytic differentiation (AML-M5b). "This is in agreement with a recent study which detected EGFR transcripts in bone marrow and blood samples from acute monocytic leukemia (AML) M5 patients." (PMID 27806094, 2016).
adamantinoma (1 paper, 2016). A low grade malignant neoplasm arising from the long bones. "During progression of adamantinoma, the epithelial cells acquire expression of FGF-2, EGF, and EGFR, accompanied by a higher proliferative activity." (PMID 27630780, 2016).
adenosquamous carcinomas of the cervix (1 paper, 2009). "The aim of this study was to investigate the presence of EGFR, PDGFRA and VEGFR2 RTKs aberrations, namely overexpression and activating gene mutations in a cohort of 30 adenosquamous carcinomas of the cervix." (PMID 19563658, 2009). "This is the most extensive analysis of EGFR, PDGFRA and VEGFR2 in cervical adenosquamous carcinomas." (PMID 19563658, 2009).
adenovirus infections (1 paper, 2019). "Here we provide the first studies showing that adenovirus infection induced stress-activated EGF receptor (EGFR) pro-inflammatory signaling prior to nuclear translocation and transcription of viral DNA in non-immune epithelial target cells." (PMID 31425554, 2019). "Third, the adenoviral RIDα protein attenuated the EGFR/NFκB signaling axis in the context of an acute adenovirus infection, and as an independently expressed transgene in cells stimulated with the pro-inflammatory cytokine TNF-α." (PMID 31425554, 2019). "A majority of our previous studies analyzing the effect of adenovirus infection on EGFR trafficking were carried out in cancer cell lines and heterologous cell models with pathological levels of EGFR (> 106 receptors/cell)." (PMID 31425554, 2019). "Since conventional tyrosine kinase inhibitors may not be effective towards transactivated EGFRs, we used a genetic approach to verify a role for stress-induced EGFR activity in NFκB-p65 signaling induced by adenovirus infection." (PMID 31425554, 2019). "Our results supported a hypothesis that stress-induced EGFR signaling, and its serotype-specific antagonism in HAdV-C2, are important factors in shaping the epithelial cell response to adenovirus infections." (PMID 31425554, 2019). "First, adenovirus infection induced an EGFR stress response that generated a phosphorylated NFκB binding site for the peptidyl-prolyl isomerase Pin1, which is known to enhance NFκB activity by countering negative feedback control through ubiquitin (Ub)-mediated NFκB degradation." (PMID 31425554, 2019).
adrenal cancer (1 paper, 2015). A carcinoma involving a adrenal gland. "A further explanation could be due to miR-7 reducing but not abolishing the expression of its targets, that a considerable reduction in EGFR expression was not achieved in vivo in the context of an established adrenal cancer xenograft with strong expression of EGFR." (PMID 26452132, 2015).
age (1 paper, 2014). A temporal measurement of the time period elapsed since an identifiable point in the life cycle of an organism. "EGFR-TKI is more effective than conventional chemotherapy in elderly patients, if we could pay attention to drug discontinuation and dose reduction due to age-related organ dysfunction." (PMID 25152277, 2014).
anaplastic gliomas (1 paper, 2014). "In the present study, we first report that EGFR amplification is also enriched in Classical anaplastic glioma samples." (PMID 24755548, 2014).
anthrax (1 paper, 2025). "How EF and LF exert opposing effects on MEK and PI3K signaling, and through what integrated mechanism EGFR and IGF1R transactivation contribute to anthrax pathogenesis, will require further investigation." (PMID 41158867, 2025).
aplastic anemia (1 paper, 2024). Anemia resulting from bone marrow failure (aplastic or hypoplastic bone marrow). "Although several drugs have been associated with aplastic anemia, its occurrence in response to Osimertinib, a third-generation epidermal growth factor receptor (EGFR) tyrosine kinase inhibitor (TKI), is extremely rare." (PMID 38454933, 2024).
arteriopathy (1 paper, 2021). "Altered Notch3 signaling has been proved in variant outside EGFr region, for example, variant L1515P, suggesting that variant outside EGFr might lead to arteriopathy by dysregulating Notch3 signaling." (PMID 34335700, 2021).
attention deficit-hyperactivity disorder (1 paper, 2014). A disorder characterized by a marked pattern of inattention and/or hyperactivity-impulsivity that is inconsistent with developmental level and clearly interferes with functioning in at least two settings (e.g. at home and at school). "YWHAZ is cocited with FZD7 in a paper on attention-deficit/hyperactivity disorder, with ATXN1 in a paper on the interaction of Akt-Phosphorylated Ataxin-1 with 14-3-3, and with SOS2 in a paper on epidermal growth factor receptor phosphorylation sites." (PMID 25148247, 2014).
autosomal recessive polycystic kidney disease (1 paper, 2022). An inherited disorder characterized by the development of cysts affecting the collecting ducts. "In mouse model of autosomal recessive polycystic kidney disease, it inhibited spectrum of key tyrosine kinases (EGFR, HER2/ErbB2, c-Src) that are associated with cell proliferation and angiogenesis." (PMID 35328738, 2022).
Azoospermia (1 paper, 2023). Absence of any measurable level of sperm,whereby spermatozoa cannot be observed even after centrifugation of the semen pellet. "In conclusion, eight hub genes, including EGFR, HSPA5, ATG3, KIAA0652, and MAPK1 were implicated in azoospermia." (PMID 36969237, 2023).
benign renal tumor (1 paper, 2019). "In the benign renal tumor, namely the cystic nephroma sample (RE0500), only EGFR was phosphorylated." (PMID 31690270, 2019).
benign salivary gland tumors (1 paper, 2025). "The GNPs-EGFR reflection measurements effectively differentiate malignant from benign salivary gland tumors." (PMID 40095737, 2025). "Increased EGFR expression has been observed in malignant compared to benign salivary gland tumors, correlating with tumor grade." (PMID 40095737, 2025). "Using immunohistochemistry and FISH analysis performed on surgical material disclosed an increased expression of EGFR in malignant as opposed to benign salivary gland tumors, correlating with the grade of the tumor." (PMID 40095737, 2025).
Bicuspid aortic valve (1 paper, 2019). The presence of an aortic valve with two instead of the normal three cusps (flaps). "Analyses completed by sex discovered dissimilar variants related to bicuspid aortic valve (BAV) in men (EGFR rs533525993 and TEX26 rs12857479) and females (NKX2‐5 rs2277923)." (PMID 30834692, 2019).
bird flu (1 paper, 2024). "Furthermore, through epitope binning analysis, we demonstrate the competence and diversity of a library of native antibodies targeting functional epitopes on a priority pathogen (H5N1 bird flu) and on glycosylated therapeutic Cetuximab antibodies against epidermal growth factor receptor." (PMID 39650601, 2024).
bladder carcinoma in situ (1 paper, 2018). Also known as carcinoma in situ of the urinary bladder or high grade intraurothelial neoplasia, this is a flat lesion of the transitional cell epithelium characterized by severe cytologic atypia. "Recently, this EGFR-targeted α-emitter bearing radiopharmaceutical has been applied in a pilot study for patients with bladder carcinoma in situ instead of the usual cystectomy." (PMID 30510514, 2018).
blepharitis (1 paper, 2024). Inflammation of the eyelids near the eyelashes. "The mechanism by which cetuximab causes blepharitis is not fully understood, but it is thought to be related to the drug’s effects on the epidermal growth factor receptor (EGFR) signaling pathway." (PMID 38337403, 2024). "This inhibition of EGFR signaling may disrupt the normal growth and differentiation of the eyelid epithelium, leading to blepharitis." (PMID 38337403, 2024).
brain glioblastoma multiforme (1 paper, 2013). "An example of EGFR-directed nanocarriers was provided through the functionalization of doxorubicin or carmustine-loaded cationic SLN with specific monoclonal antibody against EGFR for the treatment of brain glioblastoma multiforme." (PMID 24564841, 2013).
bronchial carcinoma (1 paper, 2023). "Epidermal growth factor receptor (EGFR) and matrix-metalloproteinase 9 (MMP-9) are proteins linked to hyperproliferative diseases such as bronchial carcinoma and are associated with the formation of neointimal hyperplasia in numerous studies." (PMID 36867212, 2023).
cartilage disease (1 paper, 2019). Softening and degeneration of the CARTILAGE. "In summary, decades of studies have concluded that EGFR signaling plays an essential role in cartilage development and homeostasis and therefore presents a novel target for treating cartilage diseases." (PMID 30828691, 2019).
cataract (1 paper, 2011). Partial or complete opacity of the crystalline lens of one or both eyes that decreases visual acuity and eventually results in blindness. "Thus, siRNA targeting EGFR may provide a totally new way for preventing PCO or even cataract." (PMID 21921987, 2011).
cerebral toxoplasmosis (1 paper, 2019). Infections of the brain caused by the protozoan toxoplasma gondii that primarily arise in individuals with immunologic deficiency syndromes (see also aids-related opportunistic infections). "Taken together, expression of DN EGFR enhanced protection against ocular and cerebral toxoplasmosis." (PMID 30679495, 2019). "Altogether, enhanced resistance against ocular and cerebral toxoplasmosis in Trg-DN EGFR mice occurred without an increase in local or systemic expression of immune mediators of resistance." (PMID 30679495, 2019).
cervical polyp (1 paper, 2024). A polyp that arises from the surface of the cervix. "None of the other 499 consecutive routine surgical pathology cases diagnosed as cervical polyps at Biopticka Laboratory Ltd. which were reviewed had morphological features identical to the studied tumors with EGFR mutations." (PMID 39387892, 2024).
Chlamydia pneumonia (1 paper, 2016). "The fact that EGFR and EGFR-induced signaling are not only important for viral binding and internalization of HCV but also for other viruses and intra-cellular bacteria including influenza A virus and Chlamydia pneumonia suggests a more general role of EGFR for pathogen-host interaction and entry." (PMID 26886748, 2016).
chlamydial infection (1 paper, 2014). "The decreased chlamydial infection upon EGFR inhibition was further confirmed by monitoring the chlamydial Hsp60 using Western blot analysis." (PMID 25471819, 2014). "The involvement of EGFR in chlamydial infection has been further shown in Chlamydia pneumoniae (C. pneumoniae), in which the protein Pmp21 binds to and activates EGFR to facilitate host cell entry." (PMID 25471819, 2014). "In summary, the studies included here show that chlamydial infection upregulates EGFR activity in host cells." (PMID 25471819, 2014).
Cholecystitis (1 paper, 2011). The presence of inflammatory changes in the gallbladder. "The motesanib 75-mg BID dosing cohort was suspended when an increased risk of cholecystitis was found at that dose level in other studies of motesanib as a monotherapy or in combination with carboplatin/paclitaxel and an EGFR inhibitor." (PMID 21791058, 2011).
cholecystolithiasis (1 paper, 2013). Single or multiple, ovoid or irregular, solid particles that are formed from bile, cholesterol, and calcium in the gallbladder cavity. "Meanwhile, EGFR activation is associated with MUC5AC overexpression in gallbladder epithelial cells which promotes stone formation in cholecystolithiasis." (PMID 24027752, 2013). "It has been reported that the EGFR cascade causes MUC5AC overproduction in gallbladder epithelial cells and promoting stone formation in cholecystolithiasis." (PMID 24027752, 2013). "However, because of the differences between cholecystolithiasis and hepatolithiasis and the heterogeneity between gallbladder and intrahepatic epithelial cells, whether EGFR activation is involved in MUC5AC overproduction in intrahepatic biliary epithelial cells needs to be investigated further." (PMID 24027752, 2013).
choroidal tumor (1 paper, 2024). "EGFR mutations (L858R and E709K) were detected in the resected choroidal tumor." (PMID 38962043, 2024).
chronic allograft nephropathy (1 paper, 2024). "Other studies have proposed the use of TGF-β1, AGT, and EGFR mRNA levels in urine samples of KTP as timely indicators of chronic allograft nephropathy (CAN) development." (PMID 39234105, 2024).
Chronic Obstructive Asthma (1 paper, 2022). Chronic airway obstruction caused by asthma. "EGFR up-regulation and activation contributes to increased proliferation and myofibroblast transformation in fibrocytes obtained from chronic obstructive asthma." (PMID 35634326, 2022). "We have previously demonstrated that EGFR up-regulation and activation increased fibrocyte proliferation and differentiation in chronic obstructive asthma patients." (PMID 35634326, 2022).
cicatricial alopecia (1 paper, 2024). Scarring hair loss, also known as cicatricial alopecia, is the loss of hair which is accompanied with scarring. "Our findings offer molecular insights and highlight a mechanism-based therapeutic strategy for addressing chronic folliculitis associated with EGFR-inhibitor anti-cancer therapy and cicatricial alopecia." (PMID 39521937, 2024). "Our research provides mechanistic insights behind scarring hair follicle destruction, particularly relevant for patients undergoing EGFR-inhibitor anti-cancer therapy and patients with cicatricial alopecia." (PMID 39521937, 2024). "Active STAT1 signaling could be readily detected in patient samples during EGFR-inhibitor treatment and in different types of cicatricial alopecia." (PMID 39521937, 2024). "We could readily visualize the phosphorylation of STAT1 and the upregulation of MHC-I on epidermal cells from patients under EGFR-inhibitor therapy and the pSTAT1 signature in patients with cicatricial alopecia." (PMID 39521937, 2024). "Skin biopsies from EGFR inhibitor-treated and cicatricial alopecia patients revealed an active JAK-STAT1 signaling signature along with upregulation of antigen presentation and downregulation of key components of the EGFR pathway." (PMID 39521937, 2024).
clear cell sarcoma of the kidney (1 paper, 2020). "Although clear cell sarcoma of the kidney also appears to be EGFR positive, the staining pattern is different, which might be useful diagnostically, but the number of cases tested is very small, making definitive conclusions difficult." (PMID 32490123, 2020).